TFE3 (transcription factor binding to IGHM enhancer 3)
Diseases named in the same sentence as TFE3 in open-access papers (continued):
Sharing a sentence is not in itself a finding about the gene and the disease.
tumor (continued). "In immunohistochemical analyses, tumor cells exhibit diffuse nuclear labeling for TFE3 protein and cytoplasmic reactivity with Cathepsin K and HMB45." (PMID 30103811, 2018). "IHC showed that tumor cells were diffusely positive for TFE3 and exhibited patchy and weak HMB45 staining." (PMID 30103811, 2018). "In the present case, the tumor cells with organoid architecture separated by fibrovascular network showed strong TFE3 nuclear staining, a split signal of TFE3 genes, and ASPSCR1-TFE3 fusion PCR products, suggesting Xp11.2 translocation RCC." (PMID 27733182, 2016). "Surprisingly, the tumor cells demonstrated strong nuclear and weak cytoplasmic staining for TFE3, a relatively specific IHC marker for Xp11.2 translocation RCC." (PMID 27733182, 2016). "Unlike previous reports which claimed mutually exclusive occurrence of WWTR1-CAMTA1 translocation and YAP1-TFE3 gene fusion, tumor cells from the TFE3-positive EHEs showed separate signals, indicating the presence of CAMTA1 translocations." (PMID 26840265, 2016). "Immunohistochemically (IHC), the tumor cells are positive for TFE3 and the renal tubular markers (PAX2 and PAX8), and completely negative for SMARCB1, an oncosuppressor protein." (PMID 27733182, 2016). "The term of Xp11.2 tRCC derived from several different chromosomal translocations of Xp11.2 breakpoints and formatting of TFE3 fusion gene, which resulted in a significant overexpression of TFE3 protein in tumor cells." (PMID 27893792, 2016). "Of the 76 enrolled patients, 19 (25.0%) were found strong (3+) TFE3 nuclear positivity in tumor cells, 11 (14.5%) showed moderate (2+) immunoreactivity, 26 (34.2%) showed equivocal (1+) TFE3 immunoreactivity, and 20 (26.3%) were negative for TFE3." (PMID 26880493, 2016). "The distinctive TFE3 immunostaining is widely used as a surrogate marker in enabling the diagnosis of this rare tumor." (PMID 26880493, 2016). "By IHC, the tumor cells showed diffuse and strong nucler positivity for TFE3 but negativity for all the other markers detected except for Ki67, which labeled approximate 10 % tumor cells." (PMID 26369552, 2015). "FISH assay of the tumor cells showed a single interphase nucleus with split red and green signals observed in approximate 15 % tumorous nuclei, indicating the presence of a TFE3 gene rearrangement involving X chromosome." (PMID 26369552, 2015). "TFE3, examined in 24 cases, showed a nuclear reaction, at least focally, in 21 cases (88%), including the two TFE3-rearranged neoplasms (Cases 8 and 31)." (PMID 24986479, 2014). "The protein of TFE3, located on Xp11.22, is a member of the microphtalmia transcription factor family with oncogenic properties in several tumor types." (PMID 24986479, 2014). "Immunochemistry for transcription factor E3 (TFE3) showed intense nuclear staining in the majority of the tumor cells." (PMID 25120696, 2014). "The MiTF/TFE neoplasms have in common the overexpression of MiTF and/or TFE3 or TFEB transcription factors - a subfamily in the helix-loop-helix family of transcription factors." (PMID 24735727, 2014). "This tumor is characterized by the translocation of Xp11.2, with the gene fusions involving the TFE3 transcription factor gene or TFEB." (PMID 25274276, 2014). "HIF-1α and TFE3 staining were located mostly in the nuclear of the AdCC tumor cells as compared with PA (P<0.01 for HIF-1α and P<0.001 for TFE3) and NSG (P<0.01 for HIF-1α and P<0.001 for TFE3)." (PMID 25485635, 2014). "The RCC in the current patient showed papillary architecture and clear cytoplasm, and the tumor was diagnosed by immunohistochemical findings of TFE3 protein." (PMID 22738297, 2012). "Immunohistochemistry revealed that the nuclei of many tumor cells were positive for transcription factor E3 (TFE3)." (PMID 22738297, 2012).
tumor (continued). "Diffused cytoplasmic TFE3 staining was observed predominantly in the embedded normal renal tubules and in the normal kidney adjacent to tumor although some cytoplasmic/nuclear staining was also observed (top left)." (PMID 21209915, 2010). "In support of this idea, ectopic expression of wild-type, unfused TFE3 stimulates anchorage independent tumor cell growth." (PMID 21209915, 2010). "Nuclear labeling for TFE3 is highly sensitive (97.5%) and specific (99.6%) for neoplasms bearing TFE3 gene fusions." (PMID 19450277, 2009). "However, recent advances in tumor genomics have refined RCC classification, highlighting rare molecular subtypes such as TFE3-rearranged and SMARCB1-deficient RCCs." (PMID 41743914, 2026). "Targeting CPT1A could inhibit tumor cell proliferation, suggesting that this pathway may serve as a potential therapeutic target for TFE3 rRCC." (PMID 41716419, 2026). "This TFE3/PGC-1α/CPT1A axis enhanced tumor cell proliferation, migration, and invasion." (PMID 41716419, 2026). "Accurate diagnosis, particularly the definitive molecular confirmation of ASPSCR1-TFE3 fusion, is paramount before initiating targeted therapies, as it ensures the correct patient population is selected, especially given the overlap in TFE3 positivity with other tumor types." (PMID 41446840, 2025). "A total of 100 tumor cells were detected, clearly showing TFE3-related translocation." (PMID 40177240, 2025). "The PILA-like tumor cells express TFE3 to the same extent as other tumor cells." (PMID 39917171, 2025). "In addition, we examined the protein levels of TFE3 and Lamp1 (the lysosomal biogenesis-related gene) in tumor tissues via western blot analysis." (PMID 40259886, 2025). "TFE3 breakpoints were identified in a cohort of 31 TFE3-rRCC tumor samples." (PMID 41367616, 2025). "It has been suggested that ASPS and TFE3-rearranged PEComa may represent different phenotypes of the same tumor spectrum, but its accuracy still needs to be confirmed by more subsequent studies." (PMID 40176092, 2025). "Recent studies have demonstrated that TFE-3 is diffusely expressed in this tumor type." (PMID 40860841, 2025). "In children and adolescents, a significant fraction of RCCs were historically unclassified, but many of these have since been identified as translocation carcinomas involving TFE3/TFEB or as renal medullary carcinoma (a rare tumor almost exclusive to patients with sickle cell trait)." (PMID 41426798, 2025). "Moreover, confirming the presence of WWTR1::CAMTA1 or YAP1::TFE3 gene fusion in the tumor would offer more convincing evidence." (PMID 40040722, 2025). "Notably, in the STP mice, expression of phosphorylated mTORC1 substrates were specifically increased in the TFE3 (+) tumor cells by IHC, with low expression in surrounding normal kidney." (PMID 41044182, 2025). "Recent studies have highlighted that positive TFE3 IHC is linked to tumor progression and poor prognosis, regardless of the presence of TFE3 translocation." (PMID 39470841, 2024). "The current study revealed comparable tumor characteristics between ccRCC and TFE3-rearranged-RCC." (PMID 39470841, 2024). "It is hypothesized that the TFE3 fusion proteins function like MITF in the neoplasms, and thus activate cathepsin K expression which can be detected by IHC." (PMID 37218666, 2024). "First, we confirmed the tumor-suppressive role of ARID2 in TFE3-RCC." (PMID 39727945, 2024). "Given the robust effects of DT-061 in regulating TFE3 phosphorylation and nuclear shuttling, we examined changes in p-TFE3 localization in a panel of patient-derived xenograft tumors treated with DT-061 that we previously showed to significantly inhibit tumor growth in vivo." (PMID 39349971, 2024). "In conclusion, these multifaceted and mutually corroborating experimental results strongly support our hypothesis: ARID2 likely plays a key tumor-suppressive role in TFE3-RCC." (PMID 39727945, 2024).
tumor (continued). "Here, we find that the expression of ASPSCR1::TFE3, the fusion transcription factor causatively associated with ASPS, is dispensable for in vitro tumor maintenance; however, it is required for in vivo tumor development via angiogenesis." (PMID 37029109, 2023). "Our study presents a unique insight into metabolically targeted therapy of TFE3 rRCC, which could achieve a more precise medical treatment of this tumor." (PMID 37770905, 2023). "To study whether a similar effect occurred in a mouse model, we inoculated Caki-1 cells to immunodeficient mice and found TFE3-KD inhibited tumor growth." (PMID 36935008, 2023). "In RENCA syngenic mouse tumor model, Tfe3-KD similarly decreased tumor growth." (PMID 36935008, 2023). "Therefore, epigenetic CRISPR screening with dCas9-KRAB was performed to identify ASPSCR1::TFE3 targets that are required for angiogenesis and in vivo tumor growth." (PMID 37029109, 2023). "Furthermore, TFE3, TFDP1, NFYB, and RB1, associated with the cell cycle and apoptosis, were inferred in FSTL1+ tumor cells." (PMID 37430270, 2023). "TFE3 immunohistochemistry performed on the available formalin-fixed tumor tissues from which the cell lines were derived demonstrated strong nuclear staining, and break-apart fluorescent in situ hybridization (FISH) or karyotype analysis confirming the diagnosis in all samples." (PMID 37095531, 2023). "Additionally, Fluorescence in situ hybridization (FISH) confirmed TFE3 gene rearrangement with the finding of split signal in tumor cells’ nuclei." (PMID 36647157, 2023). "The role of TFE3 in tumor cell metabolism is also summarized in this review." (PMID 36906611, 2023). "As controlling the expression level, intracellular localisation and transcriptional activity of TFE3 fusion protein are critical steps for tumour progression of Xp11.2 tRCC, we first investigated the effect of AR on the expression level of wild‐type TFE3 and TFE3 fusions." (PMID 35452181, 2022). "The TFE3 protein could inhibit the p21-mediated pRB pathway and activate the P13K/AKT/mTOR pathway, thereby leading to excessive proliferation tumor cells and ultimately causing progression of the tumors." (PMID 36276115, 2022). "More recently, some sequencing efforts revealed that the high expression of TFE3 fusions is the key factor in tumor initiation in Xp11.2 tRCC, which does not harbor any mutations of tumor driver genes." (PMID 35897085, 2022). "Each tumor had an average of 3.2 genomic alterations, and all TFE3 alterations were gene fusions." (PMID 34680376, 2021). "It’s a rare subtype characterized by several different chromosomal translocations of Xp11.2 breakpoints and involves the formatting of the transcription factor three gene (TFE3), leading to a fusion gene with a significant overexpression of TFE3 protein in tumor cells." (PMID 34257577, 2021). "In this study, we apply whole-exome sequencing (WES) on 53 TFE3-tRCCs and RNA sequencing (RNA-seq) on 63 TFE3-tRCCs to reveal their genomic and transcriptomic characteristics and discover molecular mechanisms potentially involved in tumor progression." (PMID 34489456, 2021). "Genetic abnormalities may be involved in pathogenesis; however, currently, only one case with a fusion of the genes PHF1 (PHD finger protein 1) and TFE3 (transcription factor E3), commonly found in other neoplasms, has been reported." (PMID 34064849, 2021). "Next, we explored the tumor immune microenvironment (TIME) in TFE3-tRCC." (PMID 34489456, 2021). "In this study, we propose that TFE3 but not TFEB is essential for tumour survival which was associated with the poorer survival of cancer patients." (PMID 33145941, 2020). "We have found that the expression of TFE3 is higher than TFEB in tumour cells and patients." (PMID 33145941, 2020). "TFE3 can also regulate PD‐L1 expression in ccRCC cell lines and primary human ccRCC tumour tissues." (PMID 33145941, 2020). "Their dataset contained 27 TFE3-rearranged neoplasms and 98 controls." (PMID 32286325, 2020).
tumor (continued). "In this study, we found that TFE3 is also a potent tumour promotor just like TFEB in ccRCC." (PMID 33145941, 2020). "In addition, we found that 4/10 GIST lesions showed weak TFE3 positivity, suggesting it can be a candidate marker for differentiating between these two tumor types along with CD117, Dog1 and CD34." (PMID 31043173, 2019). "Some poorly differentiated pRCCs, such as those with type 2 pathology and a large size, may present with heterogeneous enhancement due to necrosis or haemorrhage within the tumour, therefore it is difficult to be differential diagnosis from Xp11.2/TFE3 RCC." (PMID 31892340, 2019). "In addition, we compared the resultant TFE3 expression patterns with other tumor types to evaluate the specificity of this marker for DTF lesions." (PMID 31043173, 2019). "Although the immunohistochemical results, except TFE3, was little helpful for the diagnosis of this tumor, we speculated that the immunization may be associcated with sex, age, tumor morphology, size, stage, and prognosis." (PMID 29901594, 2018). "Interestingly, some of them were affecting cancer-related genes, i.e. a missense mutation in TFE3, a stop-gain mutation in KMT2C and a stop-gain mutation in the putative tumour suppressor gene RPS6KA2." (PMID 28420412, 2017). "Genetically, a subgroup of this tumor demonstrates a TFE3/TFEB rearrangement." (PMID 29053609, 2017). "Therefore, a diagnosis of Xp11.2 translocation RCC with SMARCB1 inactivation is proposed in this double hit tumor concerning the histopathological features and TFE3 rearrangement." (PMID 27733182, 2016). "Finally, primary tumor sites in TFE3-positive EHEs consistently contained single masses (P = 0.0359) with larger sizes (P = 0.0550) compared to TFE3-negative EHEs." (PMID 26840265, 2016). "Additionally, TFE3 nuclear expression in tumor cells was identified in five out of 18 cases (27.8%)." (PMID 26840265, 2016). "Type I is associated with MET alterations, whereas Type II tumours are characterized by cyclin-dependent kinase Inhibitor 2A (CDKN2A) silencing, SETD2 mutations, transcription factor E3 (TFE3) fusions and increased expression of the nuclear factor-like 2 (NRF2)–antioxidant response element pathway." (PMID 27092491, 2016). "These tumours are characterized by the occurrence of recurrent chromosomal translocations, which result in disruption and fusion of either the TFE3 or TFEB genes, both members of the MiT family of basic helix-loop-helix/leucine-zipper transcription factor genes." (PMID 24877033, 2014). "The progressive loss of tumor cells expressing the TFE3/NONO translocation was also noted in classical media." (PMID 24676409, 2014). "Correct classification of these distinct neoplasms is important as the MiTF/TFE3-related cellular pathways may eventually provide targets for novel therapeutic agents." (PMID 24735727, 2014). "These genes may be important in TFE3-mediated tumorigenesis and tumor cell survival and proliferation." (PMID 21209915, 2010). "Immunohistochemically, the tumor showed strong nuclear positivity for TFE3." (PMID 19450277, 2009). "GPNMB reactivity is non‐specific and cannot distinguish between FLCN‐mutated tumours and TFE3/TFEB RCCs, as well as various other TSC1/2/MTOR‐mutated tumours, but it may be diagnostically useful for screening for FLCN mutations that would help distinguish them from their mimics." (PMID 41384711, 2026). "The specimen was sent for further testing at the Mayo Clinic Laboratories (3050 Superior Drive NW, Rochester, MN 55901), and the tumor cells were positive for TFE3 by immunostaining; however, TFE3 fluorescence in situ hybridization testing was negative for rearrangement." (PMID 39583551, 2024). "Interestingly, the expression of ASPSCR::TFE3 is dispensable for tumor-cell maintenance in vitro; however, its expression is required for in vivo tumorigenesis and angiogenesis, and ASPSCR1::TFE3-expression loss induces drastic modifications in SE distribution." (PMID 37029109, 2023).
tumor (continued). "The similar tumor suppression and angiogenesis phenotypes and gene expression profiles between ASPSCR1::TFE3 loss and the JQ1 treatment suggests the critical role of SEs modulated by ASPSCR1::TFE3, although the mechanism by which Brd4-inhibition targets certain SEs awaits clarification." (PMID 37029109, 2023). "Finally, aberrant or equivocal TFE3 expression noted in Case 2 and in a previous case may suggest a TFE3-rearranged neoplasm." (PMID 34228212, 2022). "Finally, staining with a TFE3 antibody revealed nuclear accumulation of TFE3 in tumor cells." (PMID 32686708, 2020). "EHEs have been characterized by tumor-specific WW domain-containing transcription regulator 1(WWTR1)-calmodulin-binding transcription activator 1 (CAMTA1) translocations, and recently, a novel Yes-associated protein 1 (YAP1)-transcription factor E3 (TFE3) gene fusion was identified in EHEs." (PMID 26840265, 2016). "Interestingly, Tsc1/2 and Flcn are tumor suppressors, whereas Tfe3 is a protooncogene." (PMID 23582324, 2013). "TFE3‐RCC organoids were successfully established and passaged to investigate the anti‐tumor effect of padsevonil." (PMID 41199339, 2026). "Our data suggest that the coordinated metabolic shift via the PRCC‐TFE3/HIF1α/SREBP1 axis is a key mechanism by which PRCC‐TFE3 enhances cancer cell metabolism, promoting tumor development in TFE3‐RCC." (PMID 39807625, 2025). "In conclusion, our study elucidates a novel PRCC‐TFE3/HIF1α/SREBP1 axis that drives metabolic reprogramming and tumor growth in TFE3‐RCC." (PMID 39807625, 2025). "Remarkably, SMAPs/B56-PP2A can restore translational control in tumor cells with profound suppression of 4E-BP1 expression (e.g., many PDAC and CRC cell lines) by engaging a TFE3/TFEB→ATF4→4E-BP1 transcriptional axis." (PMID 39869680, 2025). "Histologically, EHE is a malignant tumor composed of vascular endothelial cells accompanied by a distinctive myxoid-hyaline transformation of the mesenchyme with WWTR1::CAMTA1 and YAP1::TFE3 fusion genes." (PMID 39917171, 2025). "These myoCAFs drive resistance via TFE3‐mediated autophagy and PCYT1A‐led phosphatidylcholine overproduction, creating a phospholipid‐rich niche that activates tumor HSP90/HIF1A, promoting stemness and revealing actionable therapeutic targets for HSPC." (PMID 40917018, 2025). "Taken together, these transgenic models highlight a distinct form of epithelial lineage plasticity driven by TFE3-fusions and implicate the critical role of mTOR signaling in MiT/TFE fusion-driven tumor types." (PMID 41044182, 2025). "Mechanistically, TFE3 activation upregulates phosphate cytidylyltransferase 1A (PCYT1A), driving phosphatidylcholine overproduction that activates the HSP90/HIF1A axis in tumor cells to enforce stemness." (PMID 40917018, 2025). "RNA‐seq and metabolomic analyses of the kidney tissues from these mice revealed that ketone body production is inversely correlated with tumor development, whereas de novo lipid synthesis is upregulated through the HIF1α/SREBP1‐dependent mechanism in TFE3‐RCC." (PMID 39807625, 2025). "Integrated lipidomic and functional analyses revealed that TFE3 activation drives phosphatidylcholine overproduction via direct upregulation of phosphate cytidylyltransferase 1A (PCYT1A), establishing a tumor‐promoting feedforward loop." (PMID 40917018, 2025). "Immunostaining of the tumor showed hepatocyte, arginase 1, Melan-A, HMB-45, CK20, PAX8, CD10, CA9, and TFE3 negativity, as well as AE1/AE3 and CK7 positivity, leading to the diagnosis of clear cell carcinoma of the liver." (PMID 41018392, 2025). "Immunohistochemically, the tumor demonstrated a characteristic profile with strong and diffuse positivity for CK7 and GATA3, focal positivity for CK20 and TFE3, and negativity for AMACR, CA IX, and CD10." (PMID 41367859, 2025).